LEP (leptin)
Diseases named in the same sentence as LEP in open-access papers (continued):
Sharing a sentence is not in itself a finding about the gene and the disease.
asthma (continued). "The role of adipokines quite likely varies between different asthma inflammatory processes and reported data are inconclusive regarding the independent association between serum leptin or adiponectin and the risk of asthma." (PMID 24454412, 2013). "This study evaluated the association of BMI and systemic levels of leptin and adiponectin with levels of exhaled NO and exhaled 8-isoprostanes in subjects with stable asthma and healthy controls." (PMID 17437645, 2007). "In subjects with asthma, BMI and the systemic leptin/adiponectin ratio were independently associated with a reduction in exhaled NO, and BMI was associated with increased levels of exhaled 8-isoprostanes." (PMID 17437645, 2007). "For example, a rise in leptin levels may modulate lung damage and repairs, leading to weight gain associated with asthma." (PMID 40242447, 2025). "In support of this, a meta-analysis of 13 studies with 3642 patients found that an asthma diagnosis was associated with higher leptin levels in both adults and children; however, this association disappeared in some studies when the results were adjusted for body weight." (PMID 40095561, 2025). "According to the research, asthma was also linked to elevated leptin levels." (PMID 40242447, 2025). "Furthermore, the dysregulation of adipokines, such as increased leptin and resistin and decreased adiponectin, has been observationally associated with asthma pathogenesis through inflammation and metabolic dysregulation." (PMID 41153538, 2025). "Higher leptin was associated with a lower risk of developing asthma in females, but not in males, while higher concentrations of adiponectin were associated with reduced asthma in both males and females." (PMID 39371928, 2024). "Our findings were of great implications that leptin may be a risk predictor and prognostic marker of asthma." (PMID 36914629, 2023). "Adiponectin and leptin have been considered to have different associations with asthma endotypes." (PMID 36984768, 2023). "Altered leptin signaling in utero may predispose the fetus to leptin resistance and possibly be the link to the high rates of fetal overgrowth, childhood obesity, and the risk of developing asthma later in childhood." (PMID 36645353, 2023). "In this sense, leptin increased the inflammatory response through various ways, leptin may increase the risk and severity of asthma through activating the inflammation." (PMID 36914629, 2023). "Our results indicated that leptin dysregulation may be associated with asthma risk/progression, frequent monitoring and early intervention of leptin status may be helpful for asthma prevention and therapy." (PMID 36914629, 2023). "Leptin has also been found associated with lung injury and asthma." (PMID 35769576, 2022). "Leptin, a regulator of the immune response, is implicated in the pathology of asthma." (PMID 36551211, 2022). "Generally, leptin levels are higher in women, and different leptin-associated pathologies have been more prevalent in the female population, including asthma, thus suggesting a positive association between hormonal changes caused by menopause, high leptin levels, and the severity of asthma." (PMID 36613991, 2022). "Visceral fat leptin expression is significantly associated with AHR in women with asthma." (PMID 34074279, 2021). "Importantly, a recent report indicated that increased leptin levels are associated with the severity of asthma, which is in accordance with our findings that circulating leptin contributes to systemic eosinophilic airway inflammation in both asthma and ECRS." (PMID 35046816, 2021). "Moreover, those children from obese mothers whose cord blood leptin levels are elevated, have a greater risk of asthma at three years of age (OR = 1.30; 95% CI: 1.1–1.55)." (PMID 34836093, 2021).
asthma (continued). "In addition, it has been described that the single nucleotide polymorphisms (SNPs) of the leptin and adiponectin genes have a protective effect for asthma, but that that effect is lost in obese individuals." (PMID 34836093, 2021). "BMI, adiponectin, and leptin were identified as risk factors for asthma in children." (PMID 31152468, 2019). "In conclusion, asthma in children is associated with BMI, adiponectin, and leptin." (PMID 31152468, 2019). "Thus, in contrast to the mouse models, it is unlikely that leptin-induced inflammation be the causal factor in the asthma-obesity relationship." (PMID 29486749, 2018). "In analysis of the IOW cohort, we explored whether the identified sex-related effect modification of the acetaminophen-asthma association varied across LEP and LEPR genotypes." (PMID 30231898, 2018). "Recent in vitro studies also showed that viral infection, the main cause of asthma exacerbations, led to increased secretion of leptin by bronchial epithelial cells resulting in activation of Th17 cells differentiation, and inhibition of Th2 cells differentiation." (PMID 30203371, 2018). "This investigation sought to determine whether sex modifies the acetaminophen-asthma association and whether leptin (LEP) and leptin receptor (LEPR) gene polymorphisms modulate the sex-specific associations." (PMID 30231898, 2018). "In patients with asthma, high leptin have been independently associated with the disease severity." (PMID 29686414, 2018). "Furthermore, the first randomised trial of a weight-loss regimen on improvement of asthma symptoms, showed a weak association of serum leptin with the measured total lung capacity and hyperreactivity pre- and post-intervention." (PMID 29486749, 2018). "However, taking into account an association of rs13228377 LEP polymorphism with asthma and higher leptin levels in asthma, we included them together in a predictive model." (PMID 30203371, 2018). "Moreover, the proposed mechanism of action linking acetaminophen use and leptin/leptin receptor on asthma risk seems to be further modulated by sex." (PMID 30231898, 2018). "Furthermore, a positive relationship between serum leptin and risk of asthma has been revealed by meta-analysis studies." (PMID 29891850, 2018). "Besides its proinflammatory systemic effects, leptin negatively modulates the function of regulatory T cells that are associated with asthma, and promote Th1 proliferation with increased production of interferon-γ." (PMID 24066855, 2013). "A possible explanation may be that asthma in children may be a more uniform phenotype, whereas in adults it is a heterogeneous collection of phenotypes and that leptin may be differentially associated with one of the various asthma phenotypes." (PMID 24288549, 2013). "Although murine data are convincing, it is less clear whether adiponectin, leptin, or resistin plays a role in modulating asthma risk and/or severity in human subjects, although most of the human data are still limited to association studies." (PMID 24288549, 2013). "Previously, it was shown that massive weight loss promoted an increase in adiponectin and adiponectin/leptin (A/L) ratio; additionally, a decrease in leptin levels and a reduction in exercise induced bronchospasm frequency and asthma-related symptoms, improving pro/anti-inflammatory adipokines." (PMID 24285955, 2013). "In summary, the association between leptin and obese asthma still remains inconclusive." (PMID 24025484, 2013). "It is unclear why the leptin-asthma association is more consistent among children than adults." (PMID 24288549, 2013). "A small case-control study showed that high serum leptin concentrations may discriminate women with severe asthma from mild/moderate asthma, although this association may be confounded by the remarkably different BMI values between the groups." (PMID 24288549, 2013).
asthma (continued). "Current evidence suggests that systemic leptin or visceral fat expression of leptin may be associated with greater asthma prevalence and/or severity, particularly among prepubertal boys, peripubertal and postpubertal girls, and women." (PMID 24288549, 2013). "Leptin may activate or increase the airway inflammation in asthmatics; in fact, a relationship between circulating leptin levels and risk of asthma development was observed in females." (PMID 23157852, 2012). "This may further augment asthmatic inflammation and might explain the association of leptin to asthma severity." (PMID 21615949, 2011). "Receptors for adiponectin and leptin are expressed on the airway epithelial cells, suggesting that direct effects of adipokines on the airway may be important in the pathogenesis of obesity-associated asthma." (PMID 40116547, 2025). "Therefore, the aim of this study was to assess whether short-term high-dose ICS treatment in adults with stable asthma is associated with significant metabolic changes, including alterations in leptin and glucose levels, dietary intake, and appetite." (PMID 40710443, 2025). "Moreover, excessive fat accumulation reduces levels of the anti-inflammatory adipokines, adiponectin, omentin-1, and nesfatin-1, while elevating leptin, resistin, and chemerin production, which results in a proinflammatory status associated with asthma development." (PMID 39201554, 2024). "Additionally, changes in the inflammatory cytokines from fat, such as tumor necrosis factor-alpha, leptin, and adiponectin, could increase airway sensitivity and elevate the risk of lung conditions such as asthma." (PMID 39441792, 2024). "In this sense, we speculated that leptin may also be associated with asthma risk and progression." (PMID 36914629, 2023). "Several mechanisms may explain the association between leptin status and asthma risk/progression." (PMID 36914629, 2023). "Nevertheless, our findings still had important implications that leptin level may be an auxiliary indicator for asthma susceptibility and progress due to the facts the some severe asthma cases were not obese and comprehensive analysis of multiple factors may be a better choice." (PMID 36914629, 2023). "Leptin may be a risk predictor and prognostic marker of asthma." (PMID 36914629, 2023). "The effects of leptin and adiponectin during airway development may contribute to the development of bronchial asthma, and a high prepregnancy BMI in mothers may result in an increased risk of asthma development in their children." (PMID 37780583, 2022). "Furthermore, future studies are suggested to demonstrate the role of leptin with more regulatory mechanisms in obese-associated airway inflammation in the asthma mouse model, and whether there is a regulatory feedback mechanism remains unclear." (PMID 36551211, 2022). "Moreover, a high leptin level increases the risk of developing asthma." (PMID 34948451, 2021). "LEP polymorphism may increase asthma risk via influence on its serum level." (PMID 30203371, 2018). "It is suggested that the different gender-related associations between obesity and asthma seems to be linked to hormonal characteristics in the prepubertal period (9–11 years), such as those associated with pro-inflammatory hormonal factors (e.g., leptin and adiponectin) and oestrogen." (PMID 30400197, 2018). "However, our data corroborates a recent study wherein authors observed that a decreased airway epithelial leptin/leptin R expression is associated with adult human asthma severity and airway remodeling features such as subepithelial thickness and transforming growth factor (TGF)-β." (PMID 23383125, 2013). "Consistent with this basic mechanistic data, epidemiologic studies demonstrate that higher serum leptin is associated with greater asthma prevalence and/or severity and that these associations may be stronger among women, postpubertal girls, and prepubertal boys." (PMID 24288549, 2013).
asthma (continued). "In particular, both clinical and experimental evidence suggest that leptin, an inflammatory marker, can contribute to the development of asthma by increasing airway hyperresponsiveness." (PMID 40476550, 2025). "KEGG analysis revealed that LEP was significantly enriched in pathways such as “allograft rejection,” “antigen processing,” “asthma,” “autoimmune thyroid disease,” “ECM receptor interaction,” and “graft versus host disease”." (PMID 40151199, 2025). "In contrast, OCSs are welldocumented to increase appetite, promote weight gain, and elevate adipokine levels, including leptin and adiponectin, in patients with asthma." (PMID 40710443, 2025). "The impact of weight on the interaction between IL-6 and asthma is also an important consideration as leptin can increase IL-6 levels." (PMID 39714726, 2025). "It was proposed that high BMI and leptin, along with low adiponectin, indicate severe asthma and have an asthma-predictive value, suggesting they can be used as potential indicators for future treatment." (PMID 39159917, 2025). "Significant differences were found in leptin and adiponectin levels among patients with uncontrolled and controlled asthma (p < 0.001 for leptin and adiponectin)." (PMID 40361972, 2025). "Formoterol improved adiponectin and leptin levels, enhancing asthma conditions compared to control groups, with significant body mass index differences between OAF and chromium-treated groups." (PMID 40242447, 2025). "Recent studies demonstrate a clear dose-response relationship between BMI and incident asthma in adults and highlight the role of adipokines such as leptin in mediating airway inflammation and asthma risk." (PMID 40998975, 2025). "Clinically, obese asthma patients showed higher leptin levels and stronger M1 polarization with a positive correlation between serum leptin and pro-inflammatory macrophage phenotype activity." (PMID 41516046, 2025). "Leptin levels are higher in patients with asthma than in healthy controls, and leptin expression is significantly higher in patients with worsening asthma symptoms than in asymptomatic patients." (PMID 40083433, 2025). "Lower expression levels of leptin and ObR in the bronchial epithelial cells of patients with severe asthma, compared to healthy individuals, have been documented, demonstrating an inverse relationship with airway remodeling." (PMID 40095561, 2025). "Beyond sex steroids, adipose tissue-derived hormones like leptin and adiponectin contribute to lung disease, especially asthma development and severity." (PMID 39371928, 2024). "For instance, the adipokine leptin, which regulates the immune response, plays a role in the pathology of asthma and is distributed through the lungs." (PMID 40474934, 2024). "This study found limited evidence supporting a causal relationship between adiponectin, leptin, sOB-R, resistin, RBP4, or PAI-1 and sarcoidosis, asthma, COPD, lung cancer, tuberculosis, pneumonia, or sleep apnea syndrome." (PMID 38263093, 2024). "According to previous studies, obese subjects with asthma have more leptin and less adiponectin than those with asthma." (PMID 38365763, 2024). "In asthma patients, leptin induces inflammation of lung fibroblasts by enhancing the production of further pro-inflammatory chemokines and cytokines." (PMID 38365763, 2024). "During asthma exacerbation, the serum level of adiponectin was markedly declined, whereas the leptin–adiponectin ratio was significantly elevated." (PMID 38542187, 2024). "Studies indicate a notable contribution of leptin to the pathophysiology of asthma among those who are obese." (PMID 38790590, 2024). "All of these mediators are identified as playing an important role in the pathophysiology of asthma, and, in fact, it has been demonstrated that an increasing leptin concentration is correlated with asthma exacerbation and asthma severity." (PMID 38542187, 2024).
asthma (continued). "In a systematic review, the severity of asthma symptoms or the frequency of exacerbations tended to be greater in obese individuals, who exhibited elevated levels of leptin and reduced levels of adiponectin, in contrast to their non-obese counterparts." (PMID 38790590, 2024). "Severe asthma cases showed markedly high leptin level than that in mild asthma cases among overall populations (SMD: 1.638, 95% CI: 0.952–2.323, p < 10−4) and Asians (SMD: 2.600, 95% CI: 1.854–3.345, p < 10−4)." (PMID 36914629, 2023). "Our study indicated that asthma had significantly higher level of leptin than that in non-asthma controls among overall populations, Caucasians, Asians and Africans." (PMID 36914629, 2023). "Cumulative analysis indicated that leptin status was significantly higher in severe asthma cases than that in mild asthma cases among overall populations." (PMID 36914629, 2023). "Asthma demonstrated significantly higher level of leptin than that in non-asthma controls among overall populations, Caucasians, Asians and Africans." (PMID 36914629, 2023). "Studies have found that the protein kinase C alpha (PRKCA) gene, leptin gene (LEP), and β3-adrenergic receptor gene (ADRB3) are associated with asthma and BMI." (PMID 38292857, 2023). "Severe asthma cases showed markedly higher leptin level than that in mild asthma cases among overall populations (SMD:1.638, 95% CI: 0.952–2.323, p < 10–4) and Asians (SMD:2.600, 95% CI: 1.854–3.345, p < 10–4)." (PMID 36914629, 2023). "Cumulative analyses yielded similar results regarding the difference of leptin status between asthma and non-asthma controls, as well as between severe and mild asthma cases among overall populations." (PMID 36914629, 2023). "The Begg rank correlation test and Egger linear regression test showed marked publication bias among Asians in the difference of leptin status between severe and mild asthma cases (Begg, p = 0.002; Egger, p = 0.003)." (PMID 36914629, 2023). "Serum leptin levels were positively correlated with M1 macrophage polarization levels in patients with asthma." (PMID 37488474, 2023). "Our findings suggest that obese asthma patients had elevated levels of leptin in their blood plasma, indicating systemic chronic inflammation and an inflammatory response of the adipose tissue." (PMID 37367676, 2023). "Severe asthma cases showed markedly higher leptin level than that in mild cases among overall populations and Asians." (PMID 36914629, 2023). "The Begg rank correlation test and Egger linear regression test showed marked publication bias among Asians in the difference of leptin status between asthma and non-asthma controls (Begg, p < 10−4; Egger, p < 10−4)." (PMID 36914629, 2023). "Cumulative analysis indicated that leptin status was significantly higher in asthma cases than that in non-asthma controls among overall populations." (PMID 36914629, 2023). "Increasing attention has been paid to the potential role of leptin in the development and progression of asthma." (PMID 36914629, 2023). "Obesity is associated with exacerbation of the inflammatory and immune response in asthma patients, depending on an increased synthesis of leptin, IL-6, and TNF-α." (PMID 37108123, 2023). "Asthma status was found to be positively correlated with serum leptin levels and negatively correlated with serum adiponectin levels." (PMID 36896186, 2023). "Nevertheless, no marked publication bias was observed in the studies regarding the difference of leptin level between severe and mild asthma among Caucasians, which indicated that our finding was comparatively robust." (PMID 36914629, 2023). "The Begg rank correlation test and Egger linear regression test indicated no marked publication bias among Caucasians in the difference of leptin status between severe and mild asthma cases (Begg, p = 0.230; Egger, p = 0.054)." (PMID 36914629, 2023).